EGFR (epidermal growth factor receptor)
Diseases named in the same sentence as EGFR in open-access papers (continued):
Sharing a sentence is not in itself a finding about the gene and the disease.
non-small cell lung carcinoma (continued). "The Guidelines for Clinical Practice of Molecular Tests in Non-Small Cell Lung Cancer in China (2024) stated that, in practical clinical settings, during the comprehensive analysis of acquired resistance to EGFR-TKIs, detection of NTRK fusion status is of particular importance." (PMID 41383499, 2025). "By integrating target-specific cleavage with a DNA toehold-mediated strand displacement (TMSD) reaction, they demonstrated the system’s single nucleotide specificity using the epidermal growth factor receptor (EGFR) gene from non-small cell lung cancer (NSCLC) as a target." (PMID 40149851, 2025). "Hence, high expression of FTO at the gene and protein level in EGFR-TKI-resistant cell lines strongly suggests that FTO plays a role in the development of EGFR TKI resistance in non-small cell lung cancer cells." (PMID 40722726, 2025). "This targeted therapy, effective in the treatment of EGFR mutant non-small cell lung cancer, significantly improved overall survival in a clinical trial by over 8 months for patients with advanced disease when compared with older generation tyrosine kinase inhibitors." (PMID 40117035, 2025). "In epidermal growth factor receptor (EGFR)-wild-type non-small cell lung cancer (NSCLC), stratification based on glycolytic and cholesterol-related gene expression levels highlights a subgroup of tumors with significant enrichment of cholesterol gene signatures." (PMID 40270603, 2025). "The epidermal growth factor receptor (EGFR) is considered a molecular target for the treatment of cancer due to its abnormal expression or activation in a variety of cancer cells, especially non-small-cell lung cancer (NSCLC), which accounts for 84% of lung tumors." (PMID 39859343, 2025). "The epidermal growth factor receptor (EGFR), a membrane-bound receptor tyrosine kinase (RTK), is mostly deregulated by somatic mutations and amplification and is overexpressed in different cancers such as non-small cell lung cancer, esophageal cancer, and PM." (PMID 40149313, 2025). "For example, during treatment of non-small cell lung cancer with epidermal growth factor receptor (EGFR) tyrosine kinase inhibitors (TKI), some patients may develop resistance." (PMID 41394878, 2025). "FMN was found to have the potential to become a new EGFR inhibitor and show a significant inhibitory effect on both osimertinib-sensitive and resistant non-small cell lung cancer cells, which could greatly reduce the generation of drug resistance." (PMID 40098623, 2025). "Immune checkpoint inhibitors (ICIs) combined with chemotherapy (Chemo+ICI) have shown variable benefit in patients with epidermal growth factor receptor (EGFR)-mutant non-small cell lung cancer (NSCLC) whose disease progressed following tyrosine kinase inhibitors (TKIs) therapy." (PMID 40831747, 2025). "Non-small cell lung cancer (NSCLC), particularly lung adenocarcinoma, is predominantly driven by mutations in driver genes, primarily including anaplastic lymphoma kinase (ALK) rearrangements and epidermal growth factor receptor (EGFR) mutations." (PMID 40052122, 2025). "Here, using a DNA barcoding approach, the authors demonstrate EGFR TKI treatment in non-small cell lung cancer enriches for resistant subpopulation which can be prevented by treatment with the multikinase inhibitor sorafenib via inhibition of MKNK, STAT3 and MCL1." (PMID 40846697, 2025). "Furthermore, scRNA-seq analyses of EGFR-mutant non-small cell lung cancer (NSCLC) during targeted therapy reveal dynamic alterations in key signaling pathways and the immune microenvironment." (PMID 40625354, 2025). "However, previous study reported that EGFR-TKI treatment increases the serum adiponectin levels in subjects with non-small cell lung cancer, but little is known about the molecular mechanism linking EGFR signaling or Mig-6 and adipokine secretion." (PMID 39937764, 2025).
non-small cell lung carcinoma (continued). "As a predominant oncogenic driver in non-small cell lung cancer (NSCLC), EGFR frequently undergoes amplification or mutation, with EGFR-tyrosine kinase inhibitors (EGFR-TKIs) like gefitinib and erlotinib constituting frontline therapy for advanced EGFR-mutant cases." (PMID 40533443, 2025). "The RAIN-701 trial is a preclinical model in which tarloxotinib was evaluated in patients with advanced non-small cell lung cancer (NSCLC) harboring EGFR Exon 20 insertions or HER2 activating mutations, as well as those with NRG1, EGFR, HER2, or HER4 gene fusions." (PMID 40710312, 2025). "As an example, TKIs with EGFR inhibition action are used to treat non-small cell lung cancer." (PMID 39997355, 2025). "In addition, we demonstrated that CPZ inhibited the growth/survival of the non-small cell lung cancer cell line, PC9 harboring an activating mutation (exon 19 deletion) in the epidermal growth factor receptor (EGFR) gene." (PMID 41150745, 2025). "The emergence of the epidermal growth factor receptor (EGFR) C797S mutation in the absence of T790M represents a common mechanism of acquired resistance to first-line osimertinib in non-small cell lung cancer (NSCLC), posing a significant clinical challenge." (PMID 41158851, 2025). "EGFR-targeted therapies are widely used for breast, colorectal, and non-small cell lung cancers." (PMID 39759123, 2025). "Non-small cell lung cancer (NSCLC) often harbors oncogenic driver alterations such as epidermal growth factor receptor (EGFR), anaplastic lymphoma kinase (ALK), or Kirsten rat sarcoma viral oncogene homolog (KRAS), which can be effectively targeted with tyrosine kinase inhibitors (TKIs)." (PMID 40723270, 2025). "EGFR is the epidermal growth factor receptor, may overexpressed in many cancers, for example, non-small-cell lung cancer." (PMID 40034749, 2025). "In PC9 and HCC827 non-small cell lung cancer cell lines resistant to antiblastic treatment with a tyrosine kinase inhibitor targeting epidermal growth factor receptor and overexpressing NNMT, administration of 6MeONa suppressed growth both in vitro and in vivo." (PMID 41301471, 2025). "Erlotinib is an FDA-approved non-small cell lung cancer drug, with EGFR as its primary target." (PMID 40191608, 2025). "This predilection may, in part, reflect the association between miliary metastases and epidermal growth factor receptor (EGFR)-mutant non-small cell lung cancers, as demonstrated in a population-based study." (PMID 41341403, 2025). "EGFR, one of the ERBB family tyrosine kinases, is a widely useful therapeutic target in different types of cancer, and EGFR inhibitors have been approved by the United States Food and Drug Administration for the treatment of non-small cell lung cancer and pancreatic cancer." (PMID 40693409, 2025). "Ibrutinib and osimertinib are representative examples of covalent inactivators of Bruton tyrosine kinase (BTK) for the treatment of mantle cell lymphoma and chronic lymphocytic leukemia and epidermal growth factor receptor (EGFR) for the treatment of non-small-cell lung cancer, respectively." (PMID 38891780, 2024). "With this detailed understanding of her cancer's characteristics, the treatment commenced in August 2021 with osimertinib, a third-generation EGFR tyrosine kinase inhibitor (TKI), which was chosen based on its efficacy in targeting EGFR-mutated non-small cell lung cancer." (PMID 39108772, 2024). "In this context, we present the case of a 64-year-old man of Moroccan descent, a lifelong non-smoker, diagnosed with metastatic non-small cell lung cancer characterized by a complex epidermal growth factor receptor mutation encompassing L858R and S768I." (PMID 38494473, 2024). "The NCI-H1975 EGFR T790M non-small cell lung cancer is highly metastatic." (PMID 38699639, 2024). "Mutations in the epidermal growth factor receptor (EGFR) are common in non-small cell lung cancer (NSCLC), particularly in never-smoker patients." (PMID 39021764, 2024).
non-small cell lung carcinoma (continued). "Afatinib is another EGFR inhibitor approved for the treatment of non-small-cell lung cancer." (PMID 38254833, 2024). "Additionally, it was found that osimertinib had increased efficacy in non-small-cell lung cancer and CNS metastasis compared to earlier EGFR TKIs." (PMID 38396993, 2024). "In cancers such as non-small-cell lung cancer (NSCLC), well-characterised genetic signatures have transformed management with tyrosine kinase inhibitors targeting EGFR mutations and next-generation ALK inhibitors addressing ALK mutations, resulting in significantly improved patient outcomes." (PMID 39727715, 2024). "The study noted that in non-small cell lung cancer (NSCLC), aberrant activation of the PI3K-AKT-mTOR pathway is closely associated with resistance to EGFR tyrosine kinase inhibitors (EGFR-TKIs), and that its activation is mainly caused by PIK3CA, AKT1 mutations and PTEN deletion." (PMID 39391313, 2024). "Additionally, the expression of SRPK1 is correlated with the expression of EGFR in non-small-cell lung cancer patients, and the overexpression of SRPK1 is associated with EGFR (epidermal growth factor receptor) expression." (PMID 38397980, 2024). "We conducted a case-study study on Osimertinib, the preferred regimen for first and subsequent line of therapy in epidermal growth factor receptor (EGFR)-mutated non-small cell lung cancer (NSCLC) with or without brain metastases." (PMID 38336654, 2024). "High levels of EREG expression in colorectal cancer (CRC) associate with better therapeutic outcomes, while EREG overexpression in non-small cell lung cancer may be a therapeutic target for EGFR-TKI." (PMID 38334792, 2024). "In addition to promoting the EC cell growth, IL-6 is upregulated in EGFR-mutant non-small cell lung cancer, where it suppresses T- and NK-cell functions." (PMID 38464838, 2024). "Also, olmutinib has proven effective as an EGFR inhibitor, applied in the treatment of non-small cell lung cancer (NSCLC)." (PMID 38474579, 2024). "According to a study on non-small cell lung cancer patients receiving Gefitinib therapy, the circular RNA hsa_circ_0109320 showed significantly elevated expression levels in individuals who positively responded to EGFR-TKI treatment." (PMID 38200584, 2024). "Compared to first-generation and second-generation EGFR TKIs, furmonertinib has better penetration across the blood-brain barrier and demonstrates efficacy in treating central nervous system metastases in non-small cell lung cancer, showing a favorable response rate." (PMID 38974236, 2024). "Finally, we found out that 5139 of 18,482 non-small cell lung cancer patients in Alberta from 2010–2019 had EGFR testing." (PMID 38468224, 2024). "The findings indicate that the use of LJF in treating oral mucositis resulting from EGFR TKIs in non-small cell lung cancer patients may lead to reduced side effects and improved efficacy." (PMID 39314630, 2024). "Additionally, tumor-derived exosomal circRNA_102481 has been shown to contribute to EGFR-TKIs resistance in non-small cell lung cancer via the miR-30a-5p/ROR1 axis." (PMID 38200584, 2024). "In addition, tumor hypoxia, generated by blocking angiogenesis, activates resistance to additional target receptors, such as epidermal growth factor receptor (EGFR) inhibitors in non-small cell lung cancer and in a pancreatic cancer model." (PMID 38339244, 2024). "The prevalence of EGFR amplification in non-small cell lung cancer ranges from 6–19%." (PMID 38687753, 2024). "Patients with certain driver mutations, such as epidermal growth factor receptor (EGFR) mutations and anaplastic lymphoma kinase (ALK) rearrangement in non-small cell lung cancer (NSCLC), show poor response to ICIs and may even develop HPD." (PMID 38281981, 2024).
non-small cell lung carcinoma (continued). "Additional tyrosine kinase inhibitors have since become mainstays of non-small cell lung cancer (NSCLC) treatment, including erlotinib for patients with epidermal growth factor receptor (EGFR) mutations and crizotinib for those with anaplastic lymphoma kinase-positive (ALK+) disease." (PMID 38399425, 2024). "Currently, two treatment options are available for patients with epidermal growth factor receptor (EGFR) T790M-positive non-small-cell lung cancer (NSCLC) who experienced disease progression following first- and second-generation EGFR-tyrosine kinase inhibitor (TKI) therapies in South Korea." (PMID 38918528, 2024). "Extending the focus on pulmonary delivery, oly(lactic-co-glycolic acid) porous microspheres loaded with afatinib in stearic acid-based solid lipid nanoparticles and paclitaxel were developed specifically for pulmonary delivery aimed at treating EGFR TKI-resistant non-small cell lung cancer." (PMID 38794306, 2024). "The main druggable genetic alterations in non-small cell lung cancer involved EGFR (epidermal growth factor receptor), KRAS (Kirsten rat sarcoma viral oncogene homolog), ALK (anaplastic lymphoma kinase), BRAF (V-raf murine sarcoma oncogene homolog B1), and ROS1 (c-ros oncogene 1) genes." (PMID 39199653, 2024). "The patient’s medical history revealed that, in 2018, he received a diagnosis of non-small-cell lung cancer (NSCSL) EGFR+ with multiple bone metastases, treated with Osimertinib from 2020 and Denosumab (Xgeva 120 mg IM; one administration every 28 days) from October 2020 to February 2022." (PMID 38391832, 2024). "The major indication of EGFR-targeted therapy is represented by non-small-cell lung cancer (NSCLC)." (PMID 39273318, 2024). "Moreover, In non-small cell lung cancer (NSCLC), a mutation in the EGFR kinase domain (T790M) renders it resistant to gefitinib." (PMID 38347575, 2024). "The study included 113 patients initially diagnosed with non-small cell lung cancer who underwent lung biopsy at initial biopsy and rebiopsy after progression while on epidermal growth factor receptor tyrosine kinase inhibitors (EGFR-TKIs) and/or chemotherapy from January 2018 to December 2021." (PMID 38803532, 2024). "Dihydromyricetin suppressed EGFR signaling to inhibit survivin expression, resulting in the downregulation of survivin phosphorylation and the degradation of survivin induced by ubiquitination in non-small cell lung cancer cells." (PMID 38164179, 2024). "Previous results support this hypothesis demonstrating EGFR pathway deregulation promotes the emergence of stem like properties in non-small-cell lung cancer and is predictive of worse outcome to EGFR inhibition." (PMID 39304747, 2024). "Furthermore, EGFR overexpression occurs in approximately fifty percent of patients with non-small cell lung cancer (NSCLC)." (PMID 39896136, 2024). "The EGFR, also known as erythroblastic B1 (ErbB1)/human epidermal growth factor receptor-1(HER-1), is a transmembrane receptor tyrosine kinase implicated in various cancers (e.g., non-small-cell lung cancer, metastatic CRC, glioblastoma, head-and-neck cancer, pancreatic cancer, and breast cancer)." (PMID 38275516, 2024). "In particular, EGFR mutation is common in never-smoker Asian female and previous study demonstrated that the effect of EGFR-tyrosine kinase inhibitor therapy of non-small-cell lung cancer was better response in female than male." (PMID 38728284, 2024). "The Food and Drug Administration (FDA) has approved new drugs, including mobocertinib and amivantamab, for the treatment of advanced epidermal growth factor receptor (EGFR)-expressing non-small cell lung cancer (NSCLC), with many new medicines currently in various stages of research." (PMID 38774882, 2024). "Similarly, the accumulation of LD and overexpression of stearoyl-CoA desaturase 1 (SCD1) were observed in non-small cell lung cancer (NSCLC) cells resistant to EGFR-tyrosine kinase inhibitors (TKIs)." (PMID 37841917, 2023).
non-small cell lung carcinoma (continued). "Post-surgical radiation therapy was the only prognostic factor associated with improved local tumor control, regardless of the histologic type of non-small cell lung cancer, EGFR mutation state, resected tumor volume, or chemotherapy usage." (PMID 36676186, 2023). "Meanwhile, CD151 could promote non-small cell lung cancer cell proliferation, migration, and invasion by interacting with integrin α3β1 to enhance EGFR signaling." (PMID 36941633, 2023). "For instance, gefitinib, one of the EGFR inhibitors, was initially investigated in a clinical trial for patients with advanced non-small cell lung cancer regardless of EGFR mutation status, showing a response rate of 9–12%62." (PMID 37553332, 2023). "Data from the literature hypothesize that traditional Chinese medicinal herbs might increase efficacy while reducing toxicity if administered in combination with PKI, i.e., EGFR-TKI for Advanced Non-Small-Cell Lung Cancer." (PMID 36980652, 2023). "Our previous study showed that EGFR signaling in OSCCs reduces effector T-cell infiltration and increases Treg, generating an immunosuppressive tumor microenvironment similar to that observed in non-small cell lung cancers." (PMID 36675234, 2023). "Several studies have addressed the possibility of phosphorylation and glycosylation of sEV proteins as cancer biomarkers, for example, phospho-EGFR in head and neck cancer, phospho-AKT and -ERK1/2 in non-small-cell lung cancer, and EGFR-specific N-glycan in colorectal cancer." (PMID 36797736, 2023). "Ubiquitously expressed in different tissue types, EGFR is also one of the receptors found to be altered in several cancers, particularly breast, non-small cell lung cancer (NSCLC), glioblastoma (GBM), head and neck squamous cell carcinoma (HNSCC), ovarian, and melanoma." (PMID 37296932, 2023). "Additionally, the Cobas EGFR Mutation Test v2 is an FDA-approved liquid biopsy test designed for non-small cell lung cancer (NSCLC) patients, focusing on identifying mutations in the epidermal growth factor receptor (EGFR) gene." (PMID 37568620, 2023). "Likewise, overexpression of EGFR in metastatic non-small cell lung cancer (NSCLC) makes it a prognostic biomarker." (PMID 36900109, 2023). "Additionally, treatment of xenografts derived from EGFR mutant non-small-cell lung cancer with a cystine-depleting enzyme has been shown to inhibit tumor growth in mice." (PMID 37158834, 2023). "In addition, MEG9 was significantly associated with hepatitis B virus (HBV) infection status in hepatocellular carcinoma, and epidermal growth factor receptor (EGFR) status in adenocarcinoma patients with non-small-cell lung cancer (NSCLC)." (PMID 37822927, 2023). "This study encompassed seven cases of patients who underwent a transformation from EGFR-mutant non-small cell lung cancer (NSCLC) after receiving various TKIs (Gefitinib, Afatinib, Erlotinib, or Osimertinib), ultimately transitioning to small cell lung cancer (SCLC)." (PMID 38188289, 2023). "EGFR activation induces ILT4 in non-small cell lung cancer (NSCLC) cells." (PMID 36941614, 2023). "Non-small cell lung cancer accounts for 85% of all lung cancers and over 60% express WT EGFR." (PMID 37170144, 2023). "Furthermore, the EGFR L858R mutant statuses of 40 cancerous tissues from 40 non-small cell lung cancer patients were also identified using this method." (PMID 36985054, 2023). "Moreover, defactinib monotherapy or co-administration with other agents has shown exciting therapeutic efficacy in preclinical models of ovarian cancer, PDAC, and EGFR-mutant non-small-cell lung cancer 46-48." (PMID 37554278, 2023). "Recent clinical trials with the patritumab deruxtecan (HER3-Dxd; an Ab-drug conjugate (ADC) consisting of an anti-HER3 Ab and topoisomerase I inhibitor payload) have produced impressive results in non-small cell lung cancer (NSCLC) patients with EGFR-TKI resistance." (PMID 37537339, 2023).